RPS7 (ribosomal protein S7)
Diseases named in the same sentence as RPS7 in open-access papers (continued):
Sharing a sentence is not in itself a finding about the gene and the disease.
salivary gland tumors (1 paper, 2017). "miR-21 and miR-30e may have a critical role in salivary gland tumor development with targeting RPS7 and LIMCH1 genes." (PMID 27184509, 2017).
skin toxicity (1 paper, 2018). "We hypothesize that this SNP leads to decreased activity of RPS7 and thereby decreased follicular proliferation, thereby leading to lower susceptibility to EGFR inhibitor-induced skin toxicity." (PMID 30557370, 2018).
tumor (17 papers, 2013 to 2025). "Tumour cells showed elevated stemness‐associated ribosomal genes (RPS7, RPL8, RPL30), which serve as diagnostic/prognostic biomarkers and therapeutic targets." (PMID 40770837, 2025). "Concurrently, tumour cells elevate stemness‐associated ribosomal proteins (RPS7, RPL8, RPL30), enabling evasion of TNF signalling‐mediated surveillance." (PMID 40770837, 2025). "RPS7 is reported to be overexpressed in PCa and closely associated with tumor growth and invasion via epithelial–mesenchymal transition (EMT)." (PMID 34873618, 2021). "Moreover, we show that tumour cells displayed elevated expression of stemness‐associated ribosomal genes (RPS7, RPL8, RPL30), peaking at stage T4, which correlated with poor prognosis and immune escape." (PMID 40770837, 2025). "Tumour cells with upregulated stemness‐related ribosomal proteins (RPS7/RPL30/RPL8) evade TNF‐mediated clearance." (PMID 40770837, 2025). "Meanwhile, TNFRSF18− T cells have exhibited stronger immunoregulatory activity through the TNF pathway, while tumour cells with high stemness characteristics (high expression of RPS7/RPL30/RPL8) were more resistant to TNF‐mediated immunoregulation." (PMID 40770837, 2025). "In vivo, RPS7 knockout resulted in reduced tumor growth in the liver of the orthotopic model and fewer metastatic nodules in the experimental metastasis model." (PMID 39682684, 2024). "In contrast, RPS7 over-expressed Huh7 cells resulted in larger tumor size and more tumor nodules, as well as increased lung metastasis compared to the controls." (PMID 38326908, 2024). "In this mouse model, RPS7 knockout dramatically suppressed tumor size and tumor number compared to controls." (PMID 38326908, 2024). "Preclinical studies on human HCC cell lines (MHCC97H and HLE) and in orthotopic or experimental metastasis HCC mouse models showed that CRISPR/Cas9-mediated knockout of RPS7 led to reduced growth, migration, and invasion of tumor cells in vitro." (PMID 39682684, 2024). "Ribosomal protein S7 (RPS7) inhibits tumor growth by controlling glycolysis via suppressed expression of HIF-1α and LDHB." (PMID 31146503, 2019). "Our results suggest that RPS7 plays as a tumor suppressor to inhibit the growth and glycolysis of CRC by suppressing HIF-1α." (PMID 26735579, 2016). "Tumor sizes formed by LOVO/ RPS7 shRNA and LOVO/ control cells at 35 days were 752.2 mm3 and 488.7 mm3, respectively (p = 0.038)." (PMID 26735579, 2016). "Meanwhile, the overexpression of HIF-1α can rescue the anti-tumor effect of RPS7, suggesting HIF-1α to be a potential target gene of RPS7." (PMID 26735579, 2016). "It has been reported earlier that the recruitment of SIRT7 to the promoters of genes with tumor suppressive activities such as RPS7 couples H3K18 deacetylation to transcriptional repression." (PMID 26442981, 2015). "Overexpression of RPS7 in presence of HBx led to a severe reduction in the colony formation ability of cells, clearly highlighting that RPS7 acts as a tumor suppressor to restrict the oncogenic potential of HBx-SIRT7 axis." (PMID 26442981, 2015). "The results showed that silencing of RPS7 increased the number and weight of nodules and tumor ascites in mice injected with cells treated with shRPS7 compared with mice injected with cells expressing shGFP (P < 0.05)." (PMID 24244431, 2013). "Both the in vitro anchorage-independent colony formation and in vivo animal tumor formation capability of cells were enhanced after RPS7 was depleted." (PMID 24244431, 2013). "In the TNF signalling communication network, we observed that high‐stemness tumour cells were less regulated by immune cells, suggesting a potential association between tumour cell stemness and immune evasion, consistent with poor RFS of RPS7, RPL8 and RPL30." (PMID 40770837, 2025). "Likewise, baicalein inhibited tumor growth and reduced the levels of SMYD2 and RPS7 in the tumor tissues of xenografted mice." (PMID 35955525, 2022).
tumor (continued). "Baicalein inhibited in SMYD2/RPS7 signaling pathway in tumor cells was also detected by qRT-PCR." (PMID 35432530, 2022). "Ribosomal protein S7 (RPS7) acts as a tumor suppressor in primary tumorigenesis but its role in cancer metabolism remains unclear." (PMID 26735579, 2016). "We found that the nuclear score for RPS7 was negatively correlated with HIF-1α, GLUT4 or LDHB staining in tumor tissues (p < 0.05), evidenced by the representative images showing the high expression of RPS7 corresponding to the low expressions of HIF-1α, GLUT4 or LDHB in same tissues, or vice versa." (PMID 26735579, 2016). "In addition, compared with the corresponding controls, the overexpression of RPS7 inhibited, but silencing of RPS7 promoted tumor growth by reducing or increasing the weight of tumors." (PMID 26735579, 2016). "The upregulation of RPS7 may be crucial for SMYD2-mediated tumor growth and metastasis." (PMID 33935284, 2021). "In addition, our previous study observed that the RPS7 might works as a tumor suppressor in ovarian cancer through PI3K/AKT and MAPK signal networks." (PMID 26735579, 2016). "We further examined the expression of RPS7, RPL8 and RPL30 in other tumours using the GEPIA database." (PMID 40770837, 2025). "As SMYD2 promotes tumor growth and metastasis in LUAD and activates RPS7 expression in LUAD cells, we further explored the role of RPS7 in SMYD2-regulated cell carcinogenesis and metastasis." (PMID 33935284, 2021). "Interestingly, an inhibition of RPS7 and PIM1, a member of PIM family and an important player in the control of cell growth, apoptosis and cell cycle progression, has been linked to the stabilization of the oncogene c-Myc and a reduction in tumor growth in vitro and in vivo." (PMID 34873618, 2021). "HCT116/ control cells generated the mean tumor volume of 773.3 mm3, while HCT116/ RPS7 cDNA cells generated a reduced tumor volume of 514.1 mm3 at 35 days (p = 0.032)." (PMID 26735579, 2016). "Also, the public scRNA‐seq data showed that RPS7, RPL8 and RPL30 in tumour cells were highly expressed relative to epithelial cells (Log2FC > 1)." (PMID 40770837, 2025). "To confirm whether the expression of RPS7 can up-or down-regulate HIF-1α, GLUT4 and LDHB in vivo, we performed IHC analyses on tumor sections from all the experimental groups." (PMID 26735579, 2016). "In this study, we found that RPS7 significantly inhibited the growth, proliferation and glycolysis of CRC both in vitro and in vivo, which was in correspondence with our previous study indicating RPS7 to be a tumor suppressor." (PMID 26735579, 2016).
cancer (12 papers, 2010 to 2025). A tumor composed of atypical neoplastic, often pleomorphic cells that invade other tissues. "In regulating RNA stability, ribosomal proteins (RPs) belong to a well-known family of classical RBPs, with human ribosomal protein S7 (RPS7) playing an important role in several cancers." (PMID 40275278, 2025). "RPS7 is one among the select subset of genes that have been demonstrated to be transcriptionally repressed by SIRT7-mediated H3K18 hypoacetylation on their promoters in cancer cells." (PMID 26442981, 2015). "RPS7 gene is a tumor suppressor protein, but its mechanism in cancer remains unclear." (PMID 39140365, 2024).
infection (4 papers, 2007 to 2021). The state of being infected such as from the introduction of a foreign agent such as serum, vaccine, antigenic substance or organism. "Levels of Tep1, PPO6, and RpS7 were not significantly affected by a larval infection." (PMID 31161020, 2019).
RPS7 also shares sentences with these, for which no sentence is quoted: pancreatic cancer (2 papers); acute kidney injury (1); acute myeloid leukemia (1); Ataxia (1); B-cell lymphoma (1); Bloom syndrome (1); colon cancer (1); diabetes (1); gastric cancer (1); glioma (1); invasive breast carcinoma (1); liver cirrhosis (1); melanoma (1); myelodysplastic syndrome (1); myocardial infarction (1); osteosarcoma (1); psoriasis (1); rapadilino syndrome (1); T-cell lymphoma (1); thrombosis (1); Werner syndrome (1); Williams syndrome (1).